RN7SL509P (RNA, 7SL, cytoplasmic 509, pseudogene)
Gene: Miscellaneous RNA gene on chromosome 6 (96,914,699 to 96,914,995, reverse strand). Ensembl gene ENSG00000263479.
Homologues: Orthologues: chimpanzee Metazoa_SRP (98% identical), macaque Metazoa_SRP (92% identical), guinea pig Metazoa_SRP (80% identical). Paralogues in human: RN7SL2 (86% identical), RN7SL1 (86% identical), RN7SL3 (85% identical), RN7SL47P (83% identical), RN7SL126P (82% identical), RN7SL797P (81% identical), RN7SL799P (81% identical), RN7SL11P (81% identical), RN7SL147P (81% identical), RN7SL464P (81% identical), RN7SL664P (81% identical), RN7SL804P (81% identical), and 701 more.